VDR (vitamin D receptor)
Diseases named in the same sentence as VDR in open-access papers (continued):
Sharing a sentence is not in itself a finding about the gene and the disease.
osteoporosis (continued). "For instance, the VDR Fok1 CC genotype, linked to reduced lumbar BMD in β-TM, and familial osteoporosis histories in our βTT cases suggest a shared genetic vulnerability across thalassemia syndromes." (PMID 40932695, 2025). "Their study highlights the impact of key VDR gene variants on BMD and their association with osteoporosis in a population of Northwest Indian women, shedding light on the genetic mechanisms underlying bone health." (PMID 40831018, 2025). "explored the critical role of polymorphisms in the VDR gene in determining BMD and the risk of osteoporosis, particularly in postmenopausal women." (PMID 40831018, 2025). "Considering that the patients were being treated for osteoporosis with another type of oral medication other than the VDR agonist, the osteoporosis medication was changed to the VDR agonist (0.5 μg per day)." (PMID 39997045, 2025). "The minor ‘f’ allele is linked to reduced VDR function and has been associated with lower BMD and an increased risk of osteoporosis, particularly in populations of Northwest India and Asian ethnicities." (PMID 40831018, 2025). "Vitamin D receptors (VDR) and receptor activator of nuclear factor-kappa B ligand (RANKL) play an important role in the pathogenesis of osteoporosis, as there is a correlation between the allelic polymorphism of the candidate gene and bone remodelling markers." (PMID 40629773, 2025). "For example, miR-351 has been reported to affect osteogenesis by (+)-cholesten-3-one through targeting VDR, while the progression of osteoporosis also passes through the function of miR-206, which targets HDAC4." (PMID 40863323, 2025). "Monogenic forms, often syndromic, were linked to mutations in genes such as COL1A1, COL1A2, and WNT1, whereas multifactorial osteoporosis, particularly postmenopausal, was associated with variants in LRP5, SOST, VDR, and other GWAS-identified loci." (PMID 40772209, 2025). "The patients with the AG genotype for VDR rs731236 (TaqI) appeared to be more prone to osteoporosis." (PMID 38672272, 2024). "Long-term use of VDR-agonists has been utilized for osteoporosis treatment in post-menopausal women in China." (PMID 39654170, 2024). "This is so because, in various VDR-dependent diseases such as psoriasis, osteomalacia, joint sprains, osteoporosis, inflammatory disorders, and even broken bones, topical applications of TCM formulas or herbal remedies have proven beneficial." (PMID 38318147, 2024). "The VDR haplotypes bbAATT and bbTtAa were more frequent in the osteoporosis group compared to the healthy control group." (PMID 39125794, 2024). "In general, VDR agonists are used in conjunction with certain pathological conditions (e.g., osteoporosis, chronic kidney disease, hypoparathyroidism, and secondary hyperparathyroidism) that necessitate their use." (PMID 39770528, 2024). "Third, female patients predominated among those using VDR agonists prescribed to treat or prevent osteoporosis." (PMID 39770528, 2024). "These impressive findings suggest that TCM formulas and herbs act at the molecular level to influence, for example, osteoporosis-dependent genes, particularly VDR, to promote these beneficial effects." (PMID 38318147, 2024). "Our findings demonstrate that the downregulation of VDR expression is a mediator of BMSC senescence caused by an HFD, thus providing a potential therapeutic strategy for HFD-induced osteoporosis." (PMID 38777841, 2024). "The vitamin D receptor (VDR) regulates bone development and calcium homeostasis, suggesting a central role in musculoskeletal diseases such as osteoporosis (OP)." (PMID 36980815, 2023). "By bringing together these diverse aspects, this review enhances our understanding of the VD/VDR system’s critical role in the pathogenesis of osteoporosis and highlights its significance as a potential therapeutic target." (PMID 37957749, 2023).
osteoporosis (continued). "Vitexin promotes angiogenesis and osteogenesis via the VDR/PI3K/AKT/eNOS signaling pathway in ovariectomy-induced osteoporosis of rats." (PMID 37641047, 2023). "Each of therapy types evaluated had a beneficial effect on all osteoporosis-related traits; however, the VDR gene affected only ibandronate and raloxifene treatment." (PMID 36672934, 2023). "In this review, we aim to provide a comprehensive overview of the current understanding of the VD/VDR system's role in osteoporosis pathogenesis." (PMID 37957749, 2023). "The therapeutic implications of targeting the VDR pathway for osteoporosis management are also discussed." (PMID 37957749, 2023). "By consolidating recent findings, we underscore the relevance of the VD/VDR system in the onset and progression of osteoporosis, while also highlighting potential therapeutic avenues for disease management." (PMID 37957749, 2023). "To date, although researchers have determined that vitamin D receptor (VDR) gene, collagen I-α-1 (COLIA1) gene, and estrogen receptor (ER) gene are associated with the risk of osteoporosis." (PMID 36992874, 2023). "Utilizing the keywords “vitamin D,” “vitamin D receptor,” “osteoporosis,” and “therapy,” we aim to provide an exhaustive overview of the role of the VD/VDR system in osteoporosis pathogenesis, highlighting the most recent findings in this field." (PMID 37957749, 2023). "We verified the model by detecting the serum level of 1,25‐OH vitamin D and intestinal VDR expression, and examining degree of osteoporosis by and Masson's Trichrome Stain and Trap Stain respectively." (PMID 36579449, 2023). "FokI and BsmI polymorphisms at the Vitamin D receptor (VDR) gene have been correlated with low BMD and increased risk of osteoporosis in several studies." (PMID 38003451, 2023). "The vitamin D receptor (VDR) was one of the first genes studied for its influence on osteoporosis development." (PMID 36714573, 2022). "BB and Bb genotypes of the Bsml polymorphism of the VDR gene determine higher DXA parameter values both before and after one-year denosumab therapy in postmenopausal women with osteoporosis." (PMID 36714573, 2022). "Although genetic tests concerning the relation between VDR genotypes and bone quality yield contrary results, pharmacogenetic tests on individual responses to osteoporosis treatment yield more consistent and important data." (PMID 36714573, 2022). "Nevertheless, the VDR gene (OMIM 601769), which codes the protein receptor of vitamin D, is one of the best-studied in terms of its association with osteoporosis and bone fractures." (PMID 36714573, 2022). "Polymorphisms of genes such as VDR, ER, OPG, COL1A1 and TNFα are associated with osteoporosis and fracture risk." (PMID 36362662, 2022). "More genes like interleukin 6 (IL-6), vitamin D receptor (VDR), estrogen receptor (ESR), and calcitonin receptor (CTR) as well others were suggested to be associated with osteoporosis and bone density." (PMID 34938374, 2021). "In an epidemiology study, VDR gene polymorphisms were found to be significantly associated with the decrease in BMD and increase in osteoporosis risk." (PMID 33996619, 2021). "Osteoporosis was high among women had dominant Taq1 vitamin D receptor gene while osteoporosis was less common among the homozygous Apa1 receptor gene women." (PMID 33559788, 2021). "Osteoporosis was high among women had dominant Taq1 vitamin D receptor gene, while it was less prevalent among women had homozygous Apa1 receptor gene." (PMID 33559788, 2021). "The SNPs in VDR influence the expression and function of the VDR protein, which in turn affects the risk of low BMD and osteoporosis." (PMID 34698098, 2021). "In conclusion, VDR gene variants rs7975232, rs1544410, rs731236 had a significant effect on BMD and were associated with osteoporosis risk in Saudi postmenopausal women." (PMID 34698098, 2021).
osteoporosis (continued). "Pathways associated with PTB and/or sPTB related to cortisol production activation in depression, renal secretion of drugs, transcription role of Vitamin D receptor in regulation of genes involved in osteoporosis, immune responses, and tyrosine metabolism." (PMID 33568690, 2021). "Up till now, tens of hundreds of risk genes have been identified for osteoporosis, including collagen type I α 1 gene (COL1A1), calcitonin receptor (CTR), estrogen receptor (ESR), vitamin D receptor (VDR), and so on." (PMID 32627819, 2020). "The vitamin D receptor (VDR) is yet another long-standing candidate gene of osteoporosis, given the crucial role of vitamin D on bone biology." (PMID 33162933, 2020). "VDR, therefore, is seen as one of the significant candidate genes to explore the genetic factors leading to osteoporosis." (PMID 33238893, 2020). "In line with the findings of GENOMOS, none of the classical “osteoporosis” candidate genes, such as VDR and TGFbeta, have been identified in the GWAS meta-analyses of GEFOS as associated with osteoporosis traits." (PMID 33162933, 2020). "The serum levels of VDR and CYP19A1 were reduced following the administration of TBD, suggesting that TBD is able to treat OVX-induced osteoporosis by ameliorating the levels of VDR and CYP19A1." (PMID 33178024, 2020). "In the current study, we found the interactive effect of SNP in TNF-α rs1800629 with rs3782905 in VDR gene on overall and lumbar spine osteoporosis among elderly women." (PMID 31887189, 2019). "After multivariable adjustment, significant interactions of TNF-α rs1800629 and VDR rs3782905 were observed on overall and lumbar spine osteoporosis." (PMID 31887189, 2019). "Our data suggest that the interaction of the CG/CC genotype of VDR rs3782905 with TNF-α rs1800629 GG genotype is associated with increased risks of overall and lumbar spine osteoporosis among elderly women." (PMID 31887189, 2019). "The results showed that SNP in TNF-α rs1800629 interacted with rs3782905 in VDR gene on overall and lumbar spine osteoporosis among elderly women." (PMID 31887189, 2019). "We further explored these significant interactions by estimating the adjusted OR in osteoporosis according to TNF-α status for VDR genotype (minor–major/minor–minor and major–major genotypes)." (PMID 31887189, 2019). "Four significant interaction terms between SNPs in VDR gene (rs7975232, rs1544410, rs2239185, and rs3782905) with physical activity for osteoporosis at lumbar spine in men had been reported in our prior work." (PMID 31887189, 2019). "Many previous genetic studies explored the relationship of SNPs in VDR or TNF-α gene with osteoporosis." (PMID 31887189, 2019). "We detected significant interactions between TNF-α SNP rs1800629 and VDR rs3782905 on overall and lumbar spine osteoporosis in women after covariate adjustment and type 1 error correction (all p < 0.05)." (PMID 31887189, 2019). "The model considering traditional covariates along with interaction between physical activity with SNPs in VDR gene rs7975232, rs1544410, rs2239185, and rs3782905 had good discriminatory ability in predicting osteoporosis at lumbar spine." (PMID 31887189, 2019). "On the contrary, we found that VDR rs3782905 polymorphism is interactive with TNF-α rs1800629 on overall and lumbar spine osteoporosis." (PMID 31887189, 2019). "Mencej–Bedrac reported the individual and interactive effects of variants in the VDR gene, OPG, and TNFSF11 on BMD stratified by gender and osteoporosis status." (PMID 31887189, 2019). "CCR5 Pathway in Macrophages and Transcription_Role of VDR in regulation of genes involved in osteoporosis." (PMID 30344952, 2018). "In this study, we investigated the relationship between sarcopenia (evaluated in term of fibers atrophy), vitamin d receptor protein expression and TaqI/Cdx2/FokI VDR genotypes in an Italian cohort of osteoporosis(n=44) and osteoarthritis (n=55) patients." (PMID 30574409, 2018).
osteoporosis (continued). "In this study, we investigated the relationship between sarcopenia (evaluated in term of fibers atrophy), VDR protein expression and TaqI/Cdx2/FokI VDR genotypes in an Italian cohort of osteoporosis(n=44) and osteoarthritis (n=55) patients." (PMID 30574409, 2018). "The vitamin D receptor has been observed in skeletal muscle and gradually decreases in density with aging or osteoporosis, followed by muscle atrophy and fat generation." (PMID 28299231, 2017). "In conclusion, this case-control study is first to report the influence of VDR p.Gly14Ala and p.His305Gln genetic variants on BMD and osteoporosis in the Chinese postmenopausal women." (PMID 25784778, 2015). "The aim of the study was to evaluate the potential association between genetic variants of VDR gene and bone mineral density (BMD) and osteoporosis in Chinese postmenopausal women." (PMID 25784778, 2015). "The polymorphisms of a number of genes, including vitamin D receptor, estrogen receptor α, estrogen receptor β, LRP5 and SOST, are associated with a risk of developing osteoporosis." (PMID 25815782, 2015). "In the present study, we evaluated the genetic influence of the p.Gly14Ala and p.His305Gln genetic variants of VDR gene with the susceptibility to BMD and osteoporosis in Chinese postmenopausal women." (PMID 25784778, 2015). "More epidemiological and mechanistic studies with large different ethnic populations are necessary to confirm our findings and to further evaluate the role of VDR genetic variants in regulating BMD and osteoporosis in the future." (PMID 25784778, 2015). "The mechanism underlying the association of VDR genetic variations with BMD and osteoporosis still remains uncertain." (PMID 25784778, 2015). "Genetic variations in the VDR gene have been proved to be potential associated with BMD and osteoporosis." (PMID 25784778, 2015). "Since then, a large number of epidemiologic studies have reported the VDR genetic variants (e.g., FokI (rs10735810), BsmI (rs1544410), and ApaI (rs7975232)) are associated with BMD and osteoporosis in different ethnic groups." (PMID 25784778, 2015). "Growing evidence indicates that the vitamin D receptor (VDR) gene is an important candidate gene for influencing the development of osteoporosis." (PMID 25784778, 2015). "According toits functions, VDR gene seems to be involved inthe genetic determination of bone mineral densityand osteoporosis." (PMID 23700563, 2013). "Because B6.VDR−/− knockout mice require a special diet to prevent severe osteoporosis and death, we kept wild type B6 mice on the same diet." (PMID 22242171, 2012). "Polymorphisms of the vitamin D receptor (VDR) gene have been linked to both multiple sclerosis (MS) and osteoporosis." (PMID 21545713, 2011). "However, VDR gene polymorphisms have been associated with Graves' disease in a Japanese population, and has been suggested that a Fok-I VDR gene polymorphism may predict risk of osteoporosis in such patients." (PMID 21545713, 2011). "The VDR gene acts as an important regulator of calcium metabolism and bone cell function, and it was the first candidate gene to be studied in osteoporosis." (PMID 16507122, 2006). "Thus, I proposed that the osteoporosis treatment be changed to a VDR agonist (calcitriol) and that acyclovir ointment be discontinued." (PMID 39997045, 2025). "The obtained results indicate that the rs1544410 and rs11568820 polymorphisms of the VDR gene do not affect the development of osteoporosis in the Polish population." (PMID 39859195, 2025). "Previous studies have suggested that AKT could be regulated by VDR and is a target of 1,25(OH)2D3 and VDR, and that VDR promotes the phosphorylation of the PI3K/AKT pathway in ovariectomy-induced osteoporosis of rats." (PMID 40872626, 2025). "It should be highlighted that VDR polymorphisms themself are not the only determinant of osteoporosis risk." (PMID 39859195, 2025).
osteoporosis (continued). "Furthermore, a recent study showed low VDR expression in peripheral blood mononuclear cells in osteoporosis patients." (PMID 40244065, 2025). "A few reports showed the connection of VDR SNPs to osteoporosis in the Polish population." (PMID 39859195, 2025). "Therefore, subsequent studies evaluating the effects of these factors on BMSC senescence and bone metabolism are needed to obtain additional evidence on the role of VDR activation in HFD-induced osteoporosis." (PMID 38777841, 2024). "VDR is known to be a significant target for osteoporosis treatment, and this increase in expression suggests that vitexin might exert its bone-protective effects through VDR modulation." (PMID 38318147, 2024). "Notably, vitexin was found to increase the expression of VDR in the femur tissue of osteoporosis rats." (PMID 38318147, 2024). "By activating the VDR/eNOS signaling, vitexin may promote bone angiogenesis, which in turn supports osteogenesis, thereby offering a potential strategy for osteoporosis treatment." (PMID 38318147, 2024). "Se investigó la asociación entre varios SNP en el gen VDR y el riesgo de osteoporosis." (PMID 38634084, 2024). "However, further research is needed to fully understand the complex interactions between VDR polymorphisms, BMD, and osteoporosis risk." (PMID 37957749, 2023). "The osteoporosis in RA is affected by the vitamin D receptor gene BsmI." (PMID 37849009, 2023). "Thus, the objective of the current work was to assess VDR gene polymorphisms and BMD in Egyptian RA patients and to investigate the possible risk factors of osteoporosis and of fracture." (PMID 35048212, 2022). "The vitamin D-receptor-related disruption may be responsible for rickets and osteoporosis (Abouzid)." (PMID 36077552, 2022). "In the current study, we assessed the role of three VDR gene variants (rs7975232, rs1544410, and rs731236) as the genetic determinant of BMD and osteoporosis in postmenopausal Saudis as polymorphism in this nuclear receptor gene plays a crucial role in osteoporosis pathogenesis." (PMID 34698098, 2021). "Osteoporosis was high among women had dominant Taq1 vitamin D receptor gene (65.38%), while the homozygousApa1 receptor gene might give a sort of protection against osteoporosis (80.0% of non-osteoporotic)." (PMID 33559788, 2021). "When groups were divided according to the presence or absence of osteoporosis (osteoporosis risk), BMI values differ by VDR gene polymorphisms in the case of TaqI and this difference was statistically significant (P = 0.032)." (PMID 34351532, 2021). "Studies on VDR Bsml polymorphism and susceptibility to osteoporosis are various, but the results are not consistent." (PMID 33238893, 2020). "VDR Bsml and Fokl variants were associated with the increased risk of osteoporosis in Asian postmenopausal women but not in Caucasian postmenopausal women." (PMID 31887189, 2019). "We found that the odds of overall osteoporosis among elderly women carrying CG/CC genotype of VDR rs3782905 were significantly higher than those among carrying TNF-α rs1800629 GG genotype (adjusted OR: 3.66 [95% CI: 1.62–8.26] but not among those carrying TNF-α rs1800629 AG/AA genotype." (PMID 31887189, 2019). "Vitamin D receptor (VDR), Type I collagen (COL1), estrogen receptor (ER), apolipoprotein E (ApoE), bone morphogenetic protein (BMP), LRP5 genes and polymorphisms have been also proved to be involved in osteoporosis etiology." (PMID 31113874, 2019). "On the contrary, VDR Apal polymorphism was associated with the decreased risk of osteoporosis in Caucasian postmenopausal women but not in Asian postmenopausal women." (PMID 31887189, 2019). "Results from this study suggest that the VDR p.Gly14Ala and p.His305Gln genetic variants are significantly associated with BMD and osteoporosis in Chinese postmenopausal women and might be used as molecular markers for assessing the risk of osteoporosis." (PMID 25784778, 2015).